SIRT3 (sirtuin 3)
Diseases named in the same sentence as SIRT3 in open-access papers (continued):
Sharing a sentence is not in itself a finding about the gene and the disease.
infection (continued). "H-2Kb+ cells in the spleen of Sirt3 K223R-OT1 recipients were also more than those in Sirt3 WT-OT1 at day 21 post-infection, indicating that Sirt3 K223R could promote T memory development." (PMID 34272364, 2021). "Furthermore, Sirt3 K223R CD8+ H-2Kb+ splenocytes showed much less apoptotic ratio (Annexin V+) than Sirt3 WT CD8+ H-2Kb+ splenocytes did at day 21 after LM-OVA infection." (PMID 34272364, 2021). "SIRT3-GFP localized exclusively to the mitochondria during infection (bottom)." (PMID 33857259, 2021). "Infection of Sirt3−/− BMDM did not cause a further decline of GSH or the GSH/GSSG ratio compared to uninfected Sirt3−/− or infected WT BMDM." (PMID 33531400, 2021). "However, the percentage of H-2Kb+ cells from Sirt3 K223R-OT1 donors was higher than that from Sirt3 WT-OT1 donors at day 14 to 21 after infection." (PMID 34272364, 2021). "In addition to substrates involved in mitochondrial organization, our interactome study demonstrated that SIRT3 also had infection-induced changes in interactions with substrates involved the TCA cycle, fatty-acid metabolism, and amino acid metabolism." (PMID 33857259, 2021). "In addition, Sirt3 mRNA level was markedly inhibited in the mouse lungs after infection with Mabc-R, and significantly recovered after treatment with MIT-001." (PMID 32835604, 2020). "However, observations were inconsistent regarding the function of SIRT3 in host defenses against various bacterial and fungal infections, including infections with Escherichia coli and Klebsiella pneumoniae." (PMID 32835604, 2020). "Furthermore, resveratrol (RSV), a SIRT3-activating agent, played a protective role with antimicrobial effects against Mabc-R and – S infection in mice and zebrafish (ZF)." (PMID 32835604, 2020). "Albeit not statistically significant, the levels of G-CSF, IL-1α, MCP-1/CCL2, MIP-2/CXCL2 at day 1, G-CSF, KC, MCP-1, and MIP-2 at day 2, and IL-1α, IL-1β, IL-6, IL-10, MCP-1, MIP-2, and TNF at day 3 post-infection were 1.5–4.4-fold higher in SIRT3/5−/− than in SIRT3/5+/+ mice." (PMID 31632409, 2019). "Overall, our results suggest that SIRT3 deficiency has no major impact on host defenses against infections, supporting the safety of SIRT3-oriented therapies currently under development." (PMID 28634345, 2017). "Interestingly, the protein levels and enzymatic activity of SIRT3 in mitochondria were significantly reduced upon infection with CagA+H." (PMID 29108235, 2017). "However, the infection of mice with SIRT3N87A-expressing adenovirus abrogated the protective effect of SIRT3 on NaF-induced nephrotoxicity." (PMID 28386112, 2017). "To determine whether there were any changes in SIRT3 expression following infection with various H. pylori strains, we examined whole cell SIRT3 protein levels in H. pylori-infected cells." (PMID 29108235, 2017). "However, contrary to the in vitro studies wherein Sirt1 or Sirt3 knockdown or inhibition resulted in attenuated intracellular proliferation, here in in vivo mouse model of infection, we observed increased bacterial organ loads owing to increased bacterial dissemination." (PMID 39693143, 2024). "Further, we estimated the production of another pro-inflammatory cytokine, IL-1β at 20 hr post-infection under the knockdown condition of Sirt1 and Sirt3 and observed heightened IL-1β production under knockdown of Sirt1 and Sirt3 in comparison to the scrambled infected control." (PMID 39693143, 2024). "Our finding that SIRT3 displays reduced interactions with its substrate OPA1 late in infection, and that active SIRT3 and OPA1 both inhibit virus production, led us to ask whether the SIRT3 deacetylase activity by itself has the ability to impact mitochondrial structure." (PMID 33857259, 2021). "Furthermore, although ACAA2 was reported as a likely SIRT3 substrate, it remains to be demonstrated whether ACAA2 is also a target of SIRT3 enzymatic activity during infection and which acetylation sites are regulated by SIRT3." (PMID 33857259, 2021).
infection (continued). "The most pronounced interaction change, observed immediately upon infection, was the loss of SIRT3 association (by > 3 fold, not detected at 6, 24, 48, 96, and 120 hpi) with the acetyl-CoA acyltransferase 2 (ACAA2, also known as 3-Ketoacyl-CoA thiolase), a predicted substrate of SIRT3." (PMID 33857259, 2021). "We next asked whether SIRT3 activity can modulate mitochondrial integrity during infection." (PMID 33857259, 2021). "Mechanistically, during Listeria monocytogenes infection, SENP1 accumulates in the mitochondria, facilitating the de-SUMOylation and activation of sirtuin 3 (SIRT3)." (PMID 40071948, 2025). "In peritoneal macrophages upon SIRT1 (EX-527-1 μM) or SIRT3 (3-TYP-1μM) chemical inhibitor treatment, an increase in IL-6 and IL-1β cytokine levels was observed at 6 hr post-infection." (PMID 39693143, 2024). "Patients in the low Sirt3 group had higher ScvO2, lactate, APACHE II score, SOFA score, longer ICU stays, and worse indicators of inflammation (TNF-α, IL-6) and infection (PCT) than those in the high Sirt3 group (P < 0.05)." (PMID 35729330, 2022). "Our results showed that the lower the level of Sirt3, the worse the indicators of inflammation (TNF-α, IL-6) and infection (PCT), a result that was expected." (PMID 35729330, 2022). "The SIRT3 interaction with acetyl-CoA acyltransferase 2 (ACAA2), a putative substrate involved in fatty acid beta-oxidation, is lost upon infection, leading to elevated ACAA2 acetylation levels." (PMID 33857259, 2021). "As our results indicate that SIRT3 deacetylase activity contributes to its antiviral function and that SIRT3 regulates the MMP and mitochondrial pH during infection, we investigated our acetylome dataset for the presence of putative SIRT3 substrates." (PMID 33857259, 2021). "Infection of WT BMDM with M. tuberculosis raised Atf5 mRNA levels 1.6-fold, while this was increased 2.0-fold in Sirt3−/− BMDM." (PMID 33531400, 2021). "This suggests that the host cell responds in defense by promoting SIRT3-mediated OPA1 deacetylation, and this is then counteracted by the virus later in infection." (PMID 33857259, 2021). "However, larger groups of mice and additional models should be tested to settle whether there is or not a sex-dependent impact of SIRT3 deficiency on susceptibility to infection." (PMID 28634345, 2017). "Similarly, when Sirt3 knockout mouse embryonic fibroblasts (MEFs) were challenged with various stress factors, these cells had loss of contact inhibition and were subsequently immortalized/transformed by infection with a single oncogene, suggesting that SIRT3 may function as a TS." (PMID 25332769, 2014). "Global deacetylation of matrix proteins observed upon infection enhanced glutamate flux via TCA and correlated with the early activation of SIRT3 deacetylase, which is known to mobilize mitochondrial enzymes involved in oxidative metabolism including TCA and FAO." (PMID 40880474, 2025). "We even monitored the expression profile of Sirt1 and Sirt3 in primary macrophages like peritoneal macrophages of C57BL/6 mice and observed a similar trend of elevated expression at initial (2 hr), middle (6 hr), and late (16 hr) time points post-infection." (PMID 39693143, 2024). "However, in murine model of infection, SIRT1 or SIRT3 inhibitor treatment led to increased organ burden and triggered bacterial dissemination." (PMID 39693143, 2024). "After fully optimizing the infection conditions, it was found that shSIRT1#3 and shSIRT3#2 were the sequences with the best effects on gene knockdown among the three shRNA sequences targeting SIRT1 and SIRT3." (PMID 38012584, 2023). "The Spike infection decreased NAD+-dependent protein deacetylases 3, SIRT3, that maintains mitochondrial metabolic activity (0.59-fold in Spike vs VSV-G, P = 0.0031) and translocase of the outer membrane of mitochondria, TOMM22, gene expression (0.73-fold in Spike vs VSV-G, P = 0.0229)." (PMID 37504520, 2023).
infection (continued). "Infection with M. tuberculosis produced a significant reduction in Idh2 in WT BMDM with no reduction in Sirt3−/− BMDM." (PMID 33531400, 2021). "As predicted, infection of WT but not Myd88−/−/Trif−/− BMDM showed more than 50% reduction in Sirt3 by 24 h p.i.." (PMID 33531400, 2021). "Similarly, we performed qRT-PCR analysis of proinflammatory cytokines (Tnf, Il6, and Cxcl2) in both SIRT3 WT and SIRT3 KO BMDMs or PMs, which were pretreated with 3-TYP prior to Mabc-R infection." (PMID 32835604, 2020). "SIRT3/5−/− mice were not as ill as SIRT3/5+/+ mice (P = 0.01) and had 2.3-fold less L. monocytogenes in blood collected 48 h after infection (SIRT3/5+/+ vs. SIRT3/5−/−: 3.5 ± 0.9 × 103 cfu/ml vs. 1.5 ± 0.3 × 103 cfu/ml; median ± SEM; P = 0.005)." (PMID 31632409, 2019). "In a model of fulminant E. coli peritonitis, where all deaths occurred within 3 days, bacterial loads in blood collected 18 hours post-infection (median: 4.7 × 106 CFU/ml vs 5.2 × 106 CFU/ml; P = 0.4) and survival (27% vs 27%) were identical in SIRT3+/+ and SIRT3−/− mice." (PMID 28634345, 2017). "A more convincing argument for the role of aberrant mitochondrial superoxide levels in cells lacking Sirt3 was shown using duel infection experiments with lentivirus expressing MnSOD." (PMID 22016654, 2011). "However, there is a lack of research investigating SIRT3′s role in inflammasome activation in the host response to infection." (PMID 35215060, 2022). "Infection with the PAO1 strain in BEAS-2B bronchial epithelial cells decreases the expression of PGC-1α, mitochondrial transcription factor A (TFAM), the mitochondrial-localized NAD+ deacylase sirtuin 3 (SIRT3), and nuclear factor erythroid 2-related factor 2 (NRF2)." (PMID 35215060, 2022). "Consequently, SIRT-3 activation using Resveratrol ameliorated these pathophysiological observations, indicating SIRT-3 preserves energetic pathway function during infection." (PMID 34485381, 2021). "Neither SIRT3 nor SIRT5 was critical to fight against infections." (PMID 31632409, 2019). "Expression of Hk2 was 1.6-fold higher in uninfected Sirt3−/− BMDM compared to WT and was not further increased by M. tuberculosis, suggesting that the infection-induced increase of Hk2 in WT macrophages resulted from SIRT3 downregulation." (PMID 33531400, 2021). "SIRT3 overexpression did not impact the levels of the immediate early protein IE1, while leading to decreased abundances of pUL26 and pUL99, markers of early and late stages of infection." (PMID 33857259, 2021).
heart disease (28 papers, 2013 to 2025). "Studies have shown that sirtuin 3 (Sirt3), an NAD+-dependent HDAC, is important in cardiac disease, where loss of Sirt3 amplified cardiac remodeling." (PMID 30061171, 2018). "Because of the important role that acetylation plays in cardiac function, we believe that loss of SIRT3 and resultant mitochondrial protein hyper-acetylation contributes to the heart disease of FRDA." (PMID 28542596, 2017). "Therefore, the activation of SIRT3 and lymphangiogenesis may represent a new treatment idea to reduce the incidence of heart disease caused by chemotherapy drugs." (PMID 34180125, 2021). "A large body of research indicates that the AMPK-PGC-1α-SIRT3 pathway is crucial for the prevention and treatment of heart disease." (PMID 41019998, 2025). "Sirtuin 3 (Sirt3) has emerged as a protein of particular interest to human aging and heart diseases." (PMID 39425510, 2024). "Honokiol-induced SIRT3 overexpression effects have been tested with positive results in heart disease, renal disease and vitiligo." (PMID 37345199, 2023). "SIRT3 has a wide protective role in heart disease, and targeting SIRT3 can be a new strategy for the treatment of heart disease." (PMID 32724473, 2020). "For heart disease, Honokiol activation of SIRT3 further decreases the acetylation levels of MnSOD2 and OSCP, resulting in improved mitochondrial rate of oxygen consumption and inhibition of ROS synthesis." (PMID 32724473, 2020). "As an eminent guardian of mitochondrial homeostasis, SIRT3 also plays an irreplaceable role in heart disease." (PMID 32724473, 2020). "It is gratifying that the SIRT3 activator honokiol has been proven to have cardioprotective effects 16, 137, which also provides evidence for SIRT3 as a druggable target for improving heart disease." (PMID 32724473, 2020). "The efficacy of aged hMSC transplantation therapy for ischaemic heart diseases can be improved by SIRT3 overexpression." (PMID 30091830, 2018). "Here, we summarize previous studies and provide a comprehensive analysis of the role of SIRT3 in mitochondria metabolism and bioenergetics under physiological conditions and in cardiac diseases." (PMID 30131726, 2018). "Many cardiac diseases with abnormal metabolism and energy homeostasis are liable to result in impaired SIRT3 activity in a manner similar to the FXN KO model, leading to abnormal mitochondrial protein acetylation in the heart and impaired cardiac function." (PMID 28542596, 2017). "The cardioprotective role of SIRT3 activity is well established in adult heart disease." (PMID 37957471, 2024). "The role of SIRT3 in models of cardiac disease is also under intensive investigation." (PMID 33138323, 2020). "We hypothesized that SIRT3 increases the antioxidant capacity of aged cells and improves the efficacy of human mesenchymal stem cell (hMSC) therapy for ischaemic heart diseases in aged patients." (PMID 30091830, 2018). "Recent reports show that SIRT3 is involved in the protection of several heart diseases." (PMID 29643974, 2018). "SIRT3 overexpression may represent a means by which to improve the therapeutic effect of O‐hMSC transplantation for the treatment of ischaemic heart diseases." (PMID 30091830, 2018). "Although none of the mentioned substances (honokiol, RSV, NMN) is a specific activator of SIRT3, the results are encouraging that specific activation of SIRT3 as a therapeutic strategy may have beneficial effects in heart disease." (PMID 27790619, 2016). "As we delve deeper into the role of newly-found lysine modifications in heart disease, it may also be desirable to develop chemical screens for Sirt3 and Sirt5-specific modulators." (PMID 25228883, 2014). "Therefore, the maintenance of SIRT3 activity is important for normal mitochondrial metabolism and function and this strategy can be useful for the prevention of pathological consequences of cardiac diseases." (PMID 30131726, 2018).
heart disease (continued). "Enhanced cardiac SERCA2a function due to SIRT3 overexpression is a noteworthy result because alterations to SERCA2a function are often detected in the diseased human heart, and therapies that increase cardiac SERCA2a activity may have potential for the treatment of heart disease." (PMID 34405591, 2021). "In addition, the role of SIRT3-induced autophagy and apoptosis inhibition in heart disease should not be ignored." (PMID 32724473, 2020).
kidney disease (25 papers, 2009 to 2025). "The involvement of SIRT3 deficiency in the development of renal disease through a metabolic switch has been also recently demonstrated in renal endothelial cells." (PMID 39000044, 2024). "Conversely, Sirt3 deficiency has been linked to exacerbated kidney disease in mice subjected to a high-fat diet, a condition that mimics metabolic syndrome in humans." (PMID 39911234, 2024). "Of note, while Sirt1, Sirt2 and Sirt3 are involved in renal diseases, renal hypertrophy and fibrosis in mice deficient in these genes have not been reported." (PMID 28351995, 2017). "Moreover, whole body Sirt3-deficiency has been shown to accelerate kidney disease in response to nutrient overloads." (PMID 37816025, 2023). "In order to assess whether Sirt3 deficiency was enough to cause renal disease, we examined renal function parameters in Sirt3-/- mice at 2 and 12 months of age." (PMID 37816025, 2023). "SIRT3 is modulated by diet, and to assess whether Sirt3 deficiency aggravates mitochondrial damage and accelerates kidney disease in response to nutrient overloads, wild-type (WT) and Sirt3−/− mice were fed a high-fat-diet (HFD) or standard diet for 8 months." (PMID 35955472, 2022). "In the present study, we investigated whether Sirt3 deficiency in mice could aggravate mitochondrial damage and accelerate kidney disease in response to chronic HFD feeding." (PMID 35955472, 2022). "Clinical and experimental evidence consistently demonstrates that SIRT3 expression is reduced across various nephropathies, and its expression is negatively correlated with histological injury severity." (PMID 40860195, 2025). "There is increasing evidence that SIRT3 plays an important part in the development of kidney disease." (PMID 38195573, 2024). "Sirtuin3 (SIRT3), a mitochondrial deacetylase, has been shown to be involved in various kidney diseases." (PMID 38698042, 2024). "The beneficial effect of SIRT3 activation in renal diseases has also been elucidated through its role in preserving mitochondria and particularly by regulating optic atrophy 1 (OPA1)." (PMID 39000044, 2024). "Less is known about the role of SIRT3 in regulating endothelial cell function and its impact on the progression of kidney disease." (PMID 37816025, 2023). "Increasing the expression and activity of SIRT3 can delay the development of kidney disease." (PMID 38195573, 2024). "SIRT3 has been found to be constantly downregulated in renal diseases." (PMID 39000044, 2024). "Therefore, upregulating SIRT3 may represent a novel approach for supporting endothelial cell function and preventing major complications of kidney disease." (PMID 37816025, 2023). "For this reason, modulating SIRT3 by means of specific activators, such as honokiol, may represent a promising intervention to preserve glomerular endothelial cell function during kidney disease." (PMID 37816025, 2023). "However, the impaired vascular density being present before induction of renal injury in Sirt3-deficient mice could predispose mice to increased severity of ADR-induced damage, as vascular dysfunction is a central event in development of kidney disease." (PMID 37816025, 2023). "Our data demonstrate that Sirt3 deficiency renders mice more prone to developing oxidative stress and mitochondrial abnormalities in response to HFD, resulting in more severe kidney diseases, and this suggests that mitochondria protection may be a method to prevent HFD-induced renal injury." (PMID 35955472, 2022). "Notably, in response to HFD, urinary albumin excretion was significantly higher in Sirt3−/− than in WT mice, indicating that the lack of Sirt3 made mice more susceptible to developing early and more severe renal disease." (PMID 35955472, 2022).
kidney disease (continued). "Both SIRT-3 and SIRT-6 could serve as potential targets in managing kidney diseases, particularly in the rejection processes following kidney transplantation." (PMID 40142268, 2025). "Our findings substantiate this hypothesis and indicate that, at least in our experimental setting, the hypoxic and pro-oxidant conditions observed in the absence of SIRT3 are not sufficient to induce overt renal disease, unless these mice are exposed to a second hit." (PMID 37816025, 2023).